APOE (apolipoprotein E)
Diseases named in the same sentence as APOE in open-access papers (continued):
Sharing a sentence is not in itself a finding about the gene and the disease.
atherosclerosis (continued). "Of importance to atherosclerosis risk, the fecal microbiome profile of ApoE–/– mice receiving FTX from NPX donors exhibited aberrant lipid, carbohydrate, amino acid, and xenobiotic metabolism pathways." (PMID 33914709, 2021). "For example, endothelial cell specific NF-κB inhibition in murine model of ApoE deficient mice have shown significant reduction in the atherosclerosis development." (PMID 33925294, 2021). "[64Cu]Cu-DOTA-CANF-Comb were tested preclinically in apolipoprotein E–deficient (ApoE−/−) mice atherosclerosis model and showed a remarkable sensitivity to detect atherosclerotic plaques, enabling a transfer to clinical evaluation." (PMID 34885690, 2021). "These mice harbor the progerin-producing Lmna mutation and are engineered to lack apolipoprotein E, a genetic manipulation that has been extensively demonstrated to induce atherosclerosis in rodents." (PMID 34064612, 2021). "A chronic infusion of catestatin, vasostatin-1, or vasostatin-2 suppresses the development of atherosclerosis of the aorta in apolipoprotein E-deficient mice." (PMID 34204153, 2021). "Intracellular ROS participate in NLRP3 inflammasome activation in HHcy mice model and the high-fat diet (HFD)-induced atherosclerosis model using apolipoprotein E deficient (ApoE−/−) mice." (PMID 34299310, 2021). "SIRT3 also played a role in melatonin’s decreased atherosclerosis progression in Apolipoprotein E (ApoE)-deficient mice." (PMID 34712151, 2021). "In fact, ApoE-deficient (ApoE−/−) mice are commonly used as a model of aortic atherosclerosis, sharing a greater degree of similarity to the development of atherosclerosis in humans compared to other models." (PMID 33782520, 2021). "Some studies show that IL-6 deficiency in atherosclerosis-prone apolipoprotein E-deficient mice can actually display increased atherosclerosis." (PMID 33924019, 2021). "The administration of alpha-tocopherol 50–100 mg/kg/d for 4–8 weeks in rabbits fed with a high-fat diet or atherosclerosis-prone apoE null mice caused a reduction in the atherosclerotic lesion area." (PMID 34444804, 2021). "Both processes, atherosclerosis and systemic inflammation, predispose to the development of obesity, showing that variants and protein isoforms of the APOE gene have a direct impact on metabolic disorders." (PMID 34179542, 2021). "Using atherosclerosis-prone ApoE−/− mice with global or tissue-specific CD200 deficiency, we reveal that CD200 plays a protective role in atherogenesis." (PMID 33975450, 2021). "B2 B lymphocyte depletion ameliorated atherosclerosis in ApoE−/− mice whereas its adoptive transfer aggravated atherosclerosis in lymphocyte deficient ApoE−/− Rag-2−/− mice." (PMID 33988232, 2021). "Ligation of the common carotid artery near its bifurcation in apolipoprotein E‐deficient (Apoe−/−) mice leads to rapid atherosclerosis development, which is affected by genetic backgrounds." (PMID 34110700, 2021). "By scavenging H2O2, Prdx1 suppresses the excessive activation of ECs and consequent vascular inflammation, while Prdx1 deficiency induces early atherosclerosis in ApoE‒/‒ mice." (PMID 34439492, 2021). "This cytokine has been shown to be responsible for initiating the atherosclerosis process in rodents with diminished activity of apolipoprotein E. The association between adhesion molecules, TNF-α and IL-6 is common in ESRD, promoting atherosclerosis." (PMID 34441451, 2021). "Recently, we demonstrated for apolipoprotein E deficient (Apoeˉ/ˉ) mice with pre-existing advanced atherosclerosis that inhibition of anticoagulation by protein C (Proc)-silencing resulted in atherosclerosis-associated thrombus formation." (PMID 34052976, 2021). "In contrast, LRP1 distal NPxY mutation was shown to improve dyslipidemia and atherosclerosis in ApoE−/− mice." (PMID 33500241, 2021). "To determine the mechanism underlying increase of atherosclerosis of IL-35P35 deficiency in ApoE–/– mice, we examined Tregs in aortas." (PMID 34622804, 2021).
atherosclerosis (continued). "Due to its role in lipid metabolism, apoE deficient mice (apoE-/-) became the main animal model to study atherosclerosis in cardiovascular research." (PMID 34816004, 2021). "Recently, we found that apoE KO rabbits are highly susceptible to a cholesterol diet-induced atherosclerosis." (PMID 33603774, 2021). "First, a potential role for lymphatic Cx47 in atherosclerosis was investigated using atherosclerosis-susceptible Apolipoprotein E-deficient (Apoe−/−) mice." (PMID 34072103, 2021). "Injection of ApoE-/- mice with miR-10a precursor inhibited the GATA6 expression in the endothelium of atherosclerosis-susceptible region." (PMID 34336268, 2021). "In animal experiments using apolipoprotein E-deficient mice as a model of human atherosclerosis, it has also been shown that exposure to arsenite accelerates the progression of atherosclerosis." (PMID 33451022, 2021). "Specifically, MMP9 is implicated in the pathogenesis of atherosclerosis, as its ablation protects apolipoprotein E-deficient mice against atherosclerosis." (PMID 34829669, 2021). "To determine the mechanism underlying an increase of atherosclerosis of IL-35P35 deficiency in ApoE–/– mice, we examined Tregs in the spleen and blood." (PMID 34622804, 2021). "On the contrary, A-FABP deficiency in apolipoprotein E (ApoE)–deficient mice protected against atherosclerosis and even high-fat diet–induced advanced atherosclerosis." (PMID 34502295, 2021). "Despite these significant differences, transgenic mouse models such as ApoE-deficient mice have emerged as a widely used, cheap, convenient and reliable animal model for investigation of human atherosclerosis." (PMID 34572399, 2021). "Our group showed that deficiency of Sirt6 in bone marrow-derived cells increased atherosclerosis in ApoE knockout mice due to increased expression of scavenger receptor macrophage scavenger receptor 1 (MSR1) and foam cell formation." (PMID 34712151, 2021). "In atherosclerosis-prone apolipoprotein E deficient (ApoE−/−) mice, PlGF is up-regulated in early lesions and loss of PlGF reduces plaque size and macrophage content." (PMID 34381074, 2021). "Regarding cardiovascular diseases, the preventive effects of chronic administration of LUT (25, 50, and 100 mg/kg) on atherosclerosis have been reported in ApoE-deficient mice fed a high-fat diet via an increase in PPAR-α, a marker related to lipid metabolism." (PMID 34677429, 2021). "Our objective was to fine map mouse atherosclerosis modifier genes within a genomic region known to affect lesion development in apoE-deficient (Apoe−/−) mice." (PMID 35052410, 2021). "Recent studies in apoE–/– KO mice using chemical or adenovirus associated inhibition of GsdmD expression also showed a reduction in atherosclerosis." (PMID 34395445, 2021). "Vaccination of ApoE-deficient mice with the murine ortholog of hsp27, hsp25, can reduce experimental atherosclerosis." (PMID 33924019, 2021). "We newly generated athero-prone ApoE-deficient mice in which ECs are specifically senescent (ApoE-KO/Tie2-TERF2DN-Tg) to analyze a role of EC senescence in the progression of atherosclerosis." (PMID 34272458, 2021). "Polymorphisms in the apolipoprotein E (apoE) gene are risk factors for chronic inflammatory diseases including atherosclerosis." (PMID 34425108, 2021). "In another study, milk-derived tripeptides decrease proinflammatory cytokines IL-1β, IL-6 as well as SOCS3 in the abdominal aorta of ApoE-deficient mice, thus reducing atherosclerosis development." (PMID 33801489, 2021). "In mice, overexpressing adiponectin by introducing a transgene or adenovirus vector carrying the adiponectin gene suppresses atherosclerosis in apolipoprotein E (ApoE)-deficient mice." (PMID 33410750, 2021).
atherosclerosis (continued). "Apolipoprotein E (ApoE)-deficient mice, commonly accepted as a model of atherosclerosis, also show a decrease of muscle regeneration after FAL surgery." (PMID 33652743, 2021). "Injection of IL‐2 enhanced atherosclerosis in the Apolipoprotein E deficient (ApoE−/−) mouse model whereas the disease was reduced by injection of anti‐IL‐2 antibodies." (PMID 34569651, 2021). "Our previous studies showed that exogenous agmatine inhibits atherosclerosis in apoE-knockout mice on a chow diet, which was associated with elevation of blood HDL-cholesterol and activation of β-oxidation of fatty acids in the liver." (PMID 34639029, 2021). "Our group has shown that repeated injections of adenoviral vector expressing human SAA1 in apoE−/− mice in the immune-tolerant recombination activating gene-1-deficient background increased atherosclerosis." (PMID 34944527, 2021). "The underpinning role of mtDNA damage in atherosclerosis has been interrogated in polymerase-γ proof reading deficient ApoE−/− mice (polG−/−/ApoE−/−)." (PMID 33816463, 2021). "A recent study demonstrated that ApoE isoforms directly bind to C1q protein and modulate complement-dependent synapse loss, inflammation, microglia accumulation, and atherosclerosis." (PMID 34480088, 2021). "Pharmacological inhibition of AFABP using BMS alleviated endothelial dysfunction and atherosclerosis in mice with ApoE deficiency." (PMID 33815359, 2021). "Our previous study using the ApoE-/- mouse model has shown that a repressed level of serum circulating miR-10a is associated with the development of atherosclerosis." (PMID 34336268, 2021). "As the disease progresses in the APOE 4 carriers, metabolites associated with reducing atherosclerosis and the TCA cycle and oxidative phosphorylation appeared to correlate with (and perhaps to drive) the differences between early- and late-stage AD." (PMID 35265943, 2021). "ApoE-deficient (apoE−/−) and apoE/Siglec-E-double deficient (apoE−/−/Siglec-E−/−) mice were placed on high fat diet for 3 months and their lipid profiles and severities of atherosclerosis were assessed." (PMID 33397354, 2021). "Our exome-wide association meta-analysis demonstrated that protein-coding variants in APOB and APOE associate with subclinical atherosclerosis." (PMID 32367290, 2020). "In C57B1/6 mice and in apoE-deficient mice, injection of recombinant IL-6 at supraphysiological doses enhances atherosclerosis." (PMID 32121175, 2020). "A different study on diabetic APOE-null mice subjected to pioglitazone treatment observed attenuation of atherosclerosis via RAGE-linked signalling events." (PMID 33182772, 2020). "Accordingly, GPIb inactivation leads to reduced leukocyte adhesion to the vessel wall as well as to diminished development of atherosclerotic lesions in atherosclerosis-prone apolipoprotein E-deficient (ApoE−/−) mice." (PMID 33123127, 2020). "Together, these studies show that loss of APOE leads to a dramatic increase in atherosclerosis in mouse models, an effect that appears to be mediated in large part by the increased plasma levels of TRLs and RLPs." (PMID 32849290, 2020). "Here we investigate the effect of ribose-cysteine on GSH, GPx, oxidised lipids and atherosclerosis development in apolipoprotein E-deficient (apoE-/-) mice." (PMID 32084149, 2020). "Here, we present a case of a 40-year-old male with early atherosclerosis due to severe hypertriglyceridemia which resulted from a combination of APOE gene ε2ε1 rare genotype and additional metabolic risk factors." (PMID 33537346, 2020). "Administration of perhexiline increased hepatic KLF14 expression and HDL-C plasma levels which has a protective effect against atherosclerosis in ApoE-deficient mice." (PMID 32548128, 2020).
atherosclerosis (continued). "One of the first published studies which provided experimental evidence for this process was performed with the use of apolipoprotein E-deficient mice (ApoE-/-) that develop atherosclerotic lesions and are considered as the animal model of atherosclerosis." (PMID 33172065, 2020). "Immunohistochemical staining for TRPV1 reveals positive signals confined mainly to areas of macrophages in atherosclerotic lesions of apolipoprotein E-deficient mice (ApoE–/–, a model of atherosclerosis-prone mice)." (PMID 33613196, 2020). "ApoE deficient mice are the most widely used murine models of atherosclerosis and the formation of plaques is an important indicator of atherosclerotic pathology." (PMID 32069870, 2020). "In this study, we generated a mouse model (Apoe−/−Fpn1LysM/LysM) by breeding Fpn1LysM/LysM mice with Apolipoprotein E-deficient (Apoe−/−) mice, a classic mouse model of atherosclerosis, to investigate the role of macrophage iron in atherosclerosis." (PMID 33292517, 2020). "ApolipoproteinE-deficient (ApoE−/−) mice are studied commonly to elucidate mechanisms of atherosclerosis." (PMID 32555251, 2020). "The ε3 allele of APOE promotes the clearance of TG-rich lipoproteins, and therefore helps prevent atherosclerosis." (PMID 32546237, 2020). "The role of HMGB1 in the development of atherosclerosis has been demonstrated in mice deficient in apolipoprotein E, which were fed high-fat products." (PMID 33114431, 2020). "Previous study has reported that IGF-1 can reduce inflammatory responses, suppress oxidative stress, and decrease atherosclerosis progression in ApoE-deficient mice." (PMID 32929345, 2020). "have shown that renal denervation prevented reduction of aortic distensibility in atherosclerosis prone ApoE‐deficient rats 8 weeks after intervention." (PMID 33311525, 2020). "Immunization of Apolipoprotein E‐deficient (ApoE−/−) mice with Freund's adjuvant inhibits the development of atherosclerosis." (PMID 32285594, 2020). "Methods and Results: A mouse model of advanced atherosclerosis was generated by maintaining apolipoprotein E-deficient (ApoE-/-) mice on a hypercholesterolemic diet (HCD)." (PMID 32194817, 2020). "We showed the first significant association for APOE ε2 with multiple subclinical atherosclerosis traits across multiple ethnicities, as well as clinical CHD." (PMID 32367290, 2020). "The deletion of the CCR5 gene in apolipoprotein E-deficient (ApoE-/-) mice has a protective effect on diet-induced atherosclerosis and reduces the infiltration of mononuclear and Th1 type immune response." (PMID 32194402, 2020). "APOE variant E4 is highly involved with increased risk of disease development for both AD and atherosclerosis." (PMID 33132762, 2020). "Previously, we used this ApoE deficient mouse model to explore the effects of Ron-dependent macrophage polarization on the development and progression of atherosclerosis and NASH." (PMID 32796650, 2020). "Mice deficient for apolipoprotein-E (apoE−/−) represent another atherosclerosis model, which is currently widely used." (PMID 32197550, 2020). "Oral intake of chitosan oligosaccharide also reduced the marker of atherosclerosis including the lesion area in aorta or plaque area in aortic roots, and greatly reduced cholesterol and triglyceride in apolipoprotein E deficient mice (apoE−/−)." (PMID 33339290, 2020). "The role of oxidative stress in diabetes-associated atherosclerosis was confirmed in experiments on apoE-/- mice deficient for one of the main regulators of antioxidant enzymes, glutathione peroxidase 1 (Gpx1)." (PMID 32155866, 2020).
atherosclerosis (continued). "Attempts to therapeutically target ICAM-1 to abrogate atherosclerosis in vivo have been successful in animal models; for example, ICAM-1 deficiency and anti-ICAM-1 antibody treatment protects against atherosclerosis in ApoE-deficient mice." (PMID 32208424, 2020). "In a mouse model of atherosclerosis by Apolipoprotein E (ApoE) gene knock-out, genetic P2Y12 deletion was associated with reduced lesion area, increased fibrous content at the plaque site and decreased inflammatory cell infiltration." (PMID 32092903, 2020). "In this study, the cAbVCAM1-5 Nb, was labelled via Al18F(RESCA) chemistry, and evaluated as a tracer to image atherosclerosis plaques in Apolipoprotein E-deficient (ApoE−/−) mice." (PMID 32316285, 2020). "SAA is causally implicated in atherosclerosis, since inactivation of all three inducible Saa genes in ApoE −/− mice lowers the formation of atherosclerotic plaques whereas overexpression of Saa1 or Saa3 increases atherosclerosis." (PMID 32450889, 2020). "In mouse models of atherosclerosis, such as apolipoprotein E-deficient (apoE-/-) mice with chemically induced diabetes, RAGE deficiency was shown to alleviate atherosclerotic lesion development." (PMID 32155866, 2020). "Unfortunately, knockout of ApoE−/− mice has long been known to cause severe atherosclerosis and neurological disorders, including memory and learning defects." (PMID 32366041, 2020). "Accordingly, we are in the process of generating endothelial cell‐specific BRCA2 knockout mice with an ApoE−/− background and then evaluating atherosclerosis in order to delineate the cause and effect relationship between endothelial BRCA2 and atherosclerosis." (PMID 32638521, 2020). "Specifically, atherosclerosis-prone ApoE−/− mice deficient in TLR4 or MyD88 have less atherosclerotic plaques associated with a reduction in macrophage recruitment." (PMID 33505393, 2020). "In particular, endothelial‐specific Tie1‐deficient mice display less atherosclerosis in comparison with wild‐type mice when crossed with ApoE knockout mice which are highly susceptible to atherosclerosis." (PMID 32406209, 2020). "Our group has previously shown that immunization with a low dose of the murine proprotein CRAMP was associated with decreased atherosclerosis in apoE−/− mice." (PMID 33123157, 2020). "The Apoe deficient mice, Apoe hypomorphic mice and APOE knock-in mice have been key resources in the field of atherosclerosis biology, cardiovascular disease and peripheral inflammation." (PMID 32005122, 2020). "Apolipoprotein E (APOE) is involved in the pathogenesis of atherosclerosis and conveys a higher risk of coronary artery disease (CAD)." (PMID 32546237, 2020). "Similar to LL-37 in humans, the proprotein CRAMP has been linked to atherogenesis in apoE−/− mice as suggested by experiments showing that Cramp−/− apoE−/− mice have less atherosclerosis compared to apoE−/− mice." (PMID 33123157, 2020). "Further studies have shown that both endothelial P-selectin deficiency and platelet P-selectin deficiency can reduce atherosclerosis lesions and macrophage infiltration in ApoE−/− mice with high-fat feeding." (PMID 33371312, 2020). "Dementia-prone APP23 mice crossed with atherosclerosis-prone apolipoprotein E–deficient (ApoE−/−) mice develop larger and more inflammatory aortic atherosclerotic lesions compared with ApoE−/− mice." (PMID 32130931, 2020).